IL6 (interleukin 6)
Diseases named in the same sentence as IL6 in open-access papers (continued):
Sharing a sentence is not in itself a finding about the gene and the disease.
schizophrenia (continued). "Thus, it is possible that TNF-α, but not IL-6 more potently activates indoleamine 2,3-dioxygenase and tryptophan 2,3-dioxygenas, two major rate-limiting enzymes of Kyn formation in the schizophrenia group than in the healthy control group." (PMID 34393855, 2021). "This study suggests that elevated peripheral levels of TGF-β, but not IL-6, IL-1β, TNF-α, IFN-γ or IL-10, may not only predispose one to the development of schizophrenia, but may also be a consequence of childhood trauma." (PMID 34501305, 2021). "However, there were no other significant correlations between SIRT1, IL-6, and IL-10 levels and MetS components in schizophrenia patients (all P > 0.05)." (PMID 33324265, 2020). "Our study is the first to raise the intriguing possibility that the MIA-induced disturbances in the CD200–CD200R system, as well as its negative (IL-6) and positive (IL-4) immune regulators, determine the manifestation of the schizophrenia-like behavioural disturbances." (PMID 32664639, 2020). "Moreover, IL-6 and IL-8 levels were increased in schizophrenia but not significantly increased in affective disorders." (PMID 30116031, 2019). "Furthermore, recently-published reviews indicate that high levels of inflammation and IL-6 are related to the negative symptoms of schizophrenia." (PMID 30678202, 2019). "After treatment, IL-6 decreased both in schizophrenia and MDD, while TNF-α did not change." (PMID 30766494, 2018). "While not strong enough to stand as a predictor of schizophrenia on its own, IL-6 mRNA levels may be yet another tool for clinicians to use during either an initial diagnosis or for tailoring individualized treatment plans for patients with schizophrenia." (PMID 27206977, 2016). "In this study, we demonstrate that IL-6 mRNA levels from freshly extracted peripheral blood mononuclear cells (PBMC) could be a useful and easily clinically accessible biomarker for a diagnosis of schizophrenia." (PMID 27206977, 2016). "Our results suggest that increased levels of IL-6 may occur in the absence of changed TSPO PET signal in the brains of medicated patients with recent onset of schizophrenia." (PMID 27070405, 2016). "We have not found any correlation between serum IL-6 level and schizophrenia psychopathology." (PMID 25214388, 2015). "Moreover, these bacteria produce pro-inflammatory molecules, such as lipopolysaccharides and pro-inflammatory cytokines, including IL-6 and TNF-α, which may exacerbate the processes previously discussed in relation to both schizophrenia and glucose homeostasis." (PMID 40426670, 2025). "Nevertheless, there is no data on whether the IL-6, IL-23, and Th17 (IL-17, TNF-α, IL-21 and IL-22) axis is more associated with MNP than with SNP and whether changes in this axis are associated with the G-CoDe and the phenome of schizophrenia." (PMID 36256663, 2022). "Therefore, this could be similar to the changes observed in schizophrenia: excitability could be related to IL-6 and UA, and negative and cognitive symptoms might be mediated by IL-17 and UA interactions." (PMID 35237183, 2021). "Moreover, increased IL6 reduces human hippocampal DCX+ immature neurons through apoptosis in vitro, implying that newly generated neurons may undergo apoptosis in the SEZ in the high inflammation subgroup of schizophrenia." (PMID 34911938, 2021). "Additionally, injection of IL-6, but not the other MIA-induced cytokines IL-1α, tumor necrosis factor α (TNFα), or interferon γ (IFNγ), during pregnancy was enough to cause PPI deficits, a hallmark of schizophrenia, in offspring." (PMID 25691854, 2014). "However, when tested separately, higher levels of plasma IL-6 were significantly related only to more severe negative symptoms in those with established schizophrenia (B = 1.15; 95% CI, 0.41 to 1.89; p = .002), but not in those with early schizophrenia (B = 0.34; 95% CI, −0.47 to 1.14; p = .415)." (PMID 39911538, 2025).
schizophrenia (continued). "In a later lifestyle modification study in obese, non-diabetic individuals with schizophrenia, Kuo and co-workers were not able to detect significant decrease of either CRP, TNF or IL-6 after 10 weeks of intervention." (PMID 37265560, 2023). "While the differences in IL-6 levels between TRS and treatment-responsive schizophrenia were not significant in some of these studies." (PMID 37370004, 2023). "Results in the present study reflect this evidence, since IL-6 exerts a downstream effect on TNF-α and IFN-γ, therefore playing an influential role in a non-resolving pro-inflammatory state in schizophrenia." (PMID 37723153, 2023). "Multivariable models that conditioned CRP effects on interleukin-6 signaling and body mass index supported that the CRP-schizophrenia relationship was not driven by these factors." (PMID 35385317, 2022). "In our study, only the correlation of weak strength between IL-6 levels and lower working memory BACS scores was revealed in patients with schizophrenia regardless of the disease stage." (PMID 35873262, 2022). "Of other notable signatures relevant to immune signaling, the “inflammatory response” satisfied a less stringent FDR < 0.25 but not <0.05, and the “IL-6 JAK-STAT3 signaling” and “TNF-α signaling via NF-κB” signatures were not enriched in schizophrenia." (PMID 34054608, 2021). "In contrast to the initial findings, we did not observe any changes for IL-6, TNFα and glucose in schizophrenia, nor for BDNF and IL-6 in MDD." (PMID 33653423, 2021). "We did not detect a change in either ABCB1 or ABCC1 expression in people with schizophrenia nor in the context of high inflammation, which is in keeping with the fact that ABCB1 expression is only slightly reduced by IL-6 and increased by TNFα." (PMID 30214039, 2020). "The IL1B/Il1b, IL6/Il6, or TNF/Tnf was not significantly upregulated in the schizophrenia postmortem brain sample and in the poly‐I:C model mice." (PMID 31657521, 2019). "While median levels of IL-6, IFN-γ, and IL-12 in the bipolar disorder group were near or above levels in the schizophrenia group, none were significantly different compared to either group." (PMID 29803226, 2018). "In one sample, human IL-8 (and not IL-6, TNF-α, or IL-1β) was elevated in the serum of pregnant women whose offspring went on to develop schizophrenia and correlated with brain changes in the offspring." (PMID 30225350, 2018). "In brain, we and others find an upregulation of IL-6 and IL-8 mRNA expression in the dorsal lateral prefrontal cortex (DLPFC) of people with schizophrenia compared to controls, but no change in TNFα." (PMID 28923068, 2017). "We also found that IL-6, SERPINA3 and IL-1β mRNA levels had significantly negative relationships with the volume reduction in schizophrenia, suggesting that increases in at least these three factors are linked to reduced brain volumes." (PMID 27959331, 2016). "Furthermore, elevated IL-23 and IL-6 were identified in MNP but not SNP as compared to controls, suggesting that these cytokines are characteristics of MNP rather than schizophrenia in general." (PMID 36256663, 2022). "IL-6 and IL-6R were significantly higher in patients with schizophrenia than in normal controls and IL-6 was significantly higher in TRS than in normal controls, whereas patients with non-resistant schizophrenia TRS had intermediate values." (PMID 30374300, 2018). "A study in patients with the deficit syndrome of schizophrenia—a subgroup of patients with primary negative symptoms from the illness debut—found significantly elevated IL-6 and TNF-α in patients with deficit syndrome compared to in non-deficit schizophrenia and healthy controls." (PMID 30766494, 2018). "Furthermore, we detected elevated expression of GFAP, a gliogenic (astrocyte) marker, in postmortem brains from schizophrenia patients without the 22q11.2 deletion, whereas inflammation markers (IL1B and IL6) remained unchanged." (PMID 27801899, 2016).
schizophrenia (continued). "Interleukin-6 (IL-6) levels (7 studies [230 patients]; SMD = 0.55; 95% CI 0.35–0.76; I2 = 1%) and IL-8 levels (3 studies [95 patients]; SMD = 0.46; 95% CI 0.17–0.75, I2 = 0%) were increased in schizophrenia but not significantly increased in affective disorders." (PMID 30116031, 2019).
lupus (367 papers, 2008 to 2026). "IL-6 is a critical cytokine involved in the chronic inflammation associated with lupus oral lesions." (PMID 40791585, 2025). "The SNP rs2069705 (IL6) is also associated with inflammatory diseases such as systemic lupus erythematosus, characterized by high IFN-γ concentrations, in which it influences the pathogenesis of the diseases." (PMID 39066175, 2024). "In female mice, Blimp-1 deficiency led to more IL-6 secretion by DCs, promoted Tfh cells differentiation and germinal center (GC) responses, and produced lupus-like autoantibodies." (PMID 38051200, 2024). "This phenotype was associated with a still significant constitutive IL-6 production by IL-4-deficient basophils in the lupus-like context." (PMID 38649353, 2024). "High levels of IL-6 have been associated with decreased gut barrier integrity, including in a model of lupus." (PMID 37483626, 2023). "The importance of IL-6 in lupus nephritis pathogenesis is underscored in murine studies, whereby disruption of IL-6 signaling in lupus-prone mice was associated with reduced anti-dsDNA antibody production and proteinuria and improvement in kidney function." (PMID 35571122, 2022). "Tank-deficient mice spontaneously develop lupus-like glomerular nephritis and production of autoantibodies, which is mediated by IL-6." (PMID 34819357, 2022). "In vitro, silencing endogenous IL-38 in PBMCs caused an apparent augment in the lupus-associated mediators IL-6 and APRIL (a proliferation-inducing ligand)." (PMID 34539413, 2021). "Various inflammatory cytokines, including interleukins (IL-6, IL-17, and IL-18), type I interferons, and tumor necrosis factor-α (TNFα) have been implicated in the pathogenesis of lupus." (PMID 33953971, 2021). "This is in agreement with results showing that IL-6 deficiency was able to reduce kidney pathology and was capable of diminishing lupus activity in MRL-Faslpr mice, as well as causing a prolonged survival." (PMID 33669022, 2021). "IL-6-deficient mice exhibit resistance to lymphocyte-derived DNA-induced lupus, which causes CD4+ T cell activation, anti-dsDNA autoantibody titers, proteinuria, and glomerulonephritis." (PMID 34394075, 2021). "IL-6 is known as an important pathogenic cytokine in both human and mouse lupus due to, at least partially, its ability to induce Th17 cell differentiation and IL-17 production." (PMID 31311609, 2019). "IL-6 is one of the pioneer cytokines investigated in relation to lupus; this is mainly due to its close association to B lymphocytes." (PMID 31697750, 2019). "Viral reactivation and upregulation of cytokines such as B cell activating factor and interleukin 6 have been implicated in pathogenesis of both lupus and lymphomas." (PMID 30412918, 2018). "Association between each of 135 genotyped SNPs in IFIH1 and four lupus-associated plasma mediators, IL-6, TNF-α, IFN-β, and IP-10, were investigated via linear regression." (PMID 28234905, 2017). "IRF5-deficient cDC exhibited a reduced ability to produce TNFα, IL-6, and IL-10 in lupus-prone mice." (PMID 27034965, 2016). "We reported here that deliberate inhibition of selected DLK1-Dio3 miRNAs such as miR-154, miR-379, and miR-300 significantly reduced the production of lupus-associated cytokines IFNγ, IL-1β, IL-6, and/or IL-10." (PMID 27070142, 2016). "Studies in IL-6-deficient mice have shown that they are resistant to ALD-DNA-induced lupus, which ordinarily promotes anti-dsDNA autoantibody titers, proteinuria, CD4+ T-cell activation, and glomerulonephritis." (PMID 26579125, 2015). "A recent study has shown that the transcriptional repressor Blimp-1 has a tolerogenic function in DCs, and Blimp-1-deficient DCs over-express IL-6, which lead to the development of lupus-like autoAbs." (PMID 25093822, 2014).
lupus (continued). "The aim of this case-control study was to investigate the association between the interleukin-6 −174G/C single nucleotide polymorphism and the susceptibility to dermatomyositis (DM) and systemic lupus erythematosus (SLE) in Bulgarian patients." (PMID 24106699, 2013). "Notably, CRP levels were influenced by both BMI and Alistipes, particularly in lupus individuals with higher BMI, and elevated IL-6 was associated with higher CRP in this subgroup." (PMID 41289287, 2025). "Recently, a study in NZB/W-F1 lupus mice with behavioral deficits revealed that microglial activation in the hippocampus, a key brain region involved in memory and emotion, is associated with locally increased IL-6 levels." (PMID 38600510, 2024). "Through cumulative disruption of neuron health and function, glial reactivity, potentially under IL-6’s regulation, could be disrupting neurologic function in key brain regions to promote the neuropsychiatric disease associated with lupus." (PMID 38600510, 2024). "IL-6 also acts as a stimulant for B cell proliferation and it enhances plasma cell generation and antibody production, potentially inducing a pathogenic IgG autoantibody response as has been described in a murine model of lupus." (PMID 36726987, 2022). "IL-10, TNF-α and IL-6 have been implicated in lupus pathogenesis." (PMID 36505418, 2022). "The fact that IFN-γ and IL-6 significantly down-regulated Trap1 in vitro suggests that those cytokines or other lupus-associated cytokines may similarly influence Trap1 expression in patients, potentially not exclusively in the spleen." (PMID 33746957, 2021). "Finally, an association between IL-6 and progression of lupus has been demonstrated using several murine models of SLE." (PMID 33392201, 2020). "However, MZ B cells can secret IL6 upon the treatment of LPS in combination with CD40L, indicating the different underlying mechanisms for IL10 and IL6 production by MZ B cells in lupus-prone mice." (PMID 26068236, 2015). "The recent report showing that Blimp-1 deficiency in DCs resulted in a lupus phenotype that was dependent on IL-6 production led us to investigate whether the high level of IL-6 production by TC DCs was due to a Blimp-1 deficiency." (PMID 25093822, 2014). "In addition, elevated serum IL-6 concentrations have been reported in patients with idiopathic PH or PH associated with inflammatory diseases such as scleroderma and lupus." (PMID 22194859, 2011). "A study examining the peripheral blood of lupus patients demonstrated that Type I interferons and Th17 pathways co-regulate pathogenic immune responses in SLE, with IL-6 serving as a key link." (PMID 41008557, 2025). "Previous studies have reported that a few inflammatory cytokines have associations with systemic lupus erythematosus (SLE)—for example, IL-6, IL-17, and macrophage inflammatory protein (MIP)." (PMID 36741410, 2022). "Moreover, the histone peptide Th cell epitopes, which were also shared by autoantibody producing B cell epitopes in lupus, could inhibit production of pathogenic autoantibodies by PBMC from active lupus patients as potently as an anti-IL6 antibody." (PMID 33936042, 2021). "A close association between expression of IL6 and progression of lupus-like diseases has been described for several mouse models of SLE." (PMID 27050763, 2016). "Elevated D-dimer (>3 μg/mL), C-reactive protein, ferritin, white blood cell count, and IL-6; Lupus Anticoagulant positivity; fibrinogen > 8 g/L." (PMID 40564053, 2025). "Probiotics like L. rhamnosus LC-STH-13 inhibit NF-κB activation by blocking TLR9 signaling and preventing IκBα degradation, thus reducing pro-inflammatory cytokines such as TNF-α, IL-6, and IL-1β in lupus-prone mice." (PMID 40534849, 2025). "In various autoimmune conditions including systemic lupus erythematosus and systemic sclerosis, transitional B cells produce excessive amounts of IL-6, driven by type-1 interferon and toll-like receptor-7 activation." (PMID 40259340, 2025).
lupus (continued). "IL-1 has been shown to potentiate the effects of TNF-α and IL-6, worsening mucosal tissue damage in lupus patients." (PMID 40791585, 2025). "Salivary and tissue samples from lupus patients show elevated IL-6 levels, further highlighting its contribution to disease progression." (PMID 40791585, 2025). "Previously, it was found that IFN-γ–enhanced IL-6 production by B cells facilitated germinal centre formation and autoantibody production in a lupus mouse model." (PMID 38479808, 2025). "These benign neoplasms secrete interleukin-6 (IL-6), producing constitutional symptoms, cytopenias, and elevated inflammatory markers that can mimic systemic lupus erythematosus (SLE) flares or infections like tuberculosis (TB)." (PMID 41552135, 2025). "Recent studies in mice have enhanced our understanding of how several pro-inflammatory cytokines, including interferon (IFN)-I, tumor necrosis factor (TNF)-α, and interleukin (IL)-6, inhibit the development and generation of lupus B cells." (PMID 39917309, 2025). "It has been reported that there is an increased B cell response to IL-6 in lupus patients, and the inhibition of IL-6 levels in identified lupus patients helps to restore the balance of these naive B cells and T cells." (PMID 40585331, 2025). "IL-6 was indeed significantly increased in lupus mouse serum (MRL/lpr: 12.6 ± 2.4 pg/mL (n = 20) vs MRL/mpj: 1.7 ± 0.7 pg/mL (n = 17); ***p = 0.0003)." (PMID 38600510, 2024). "Lupus mice exhibit upregulated expression of both inflammatory (i.e., IL-17, IL-6) and anti-inflammatory (i.e., IL-10) cytokines in brain tissue, a finding readily seen in the periphery of lupus patients." (PMID 38600510, 2024). "Conversely, short term augmentation of IL-6 levels systemically was sufficient to acutely induce anhedonia in non-lupus mice." (PMID 38600510, 2024). "It has been observed that MSCs derived from human embryonic stem cells possess the ability to decrease the levels of serum IL-6 in mice prone to lupus and can potentially hinder or decelerate the progression of lupus-related glomerular disease." (PMID 39273032, 2024). "NEU1 activity promotes IL-6 secretion from lupus-prone MRL/lpr primary mouse mesangial cells (MCs) in response to an IgG mimic, and to circulating lupus factors through the TLR4-MAPK p38 or ERK signaling pathway." (PMID 39194692, 2024). "To expand upon the clinical fidelity of this model, we additionally performed a high-throughput proteomic screen of the CSF of a lupus mouse model, and we discovered several inflammatory mediators, including IL-6, found also in CSF from human NPSLE patients." (PMID 38600510, 2024). "While not addressed by the present study, identifying the origin of intrathecal inflammatory markers, including IL-6, is an active focus of lupus research." (PMID 38600510, 2024). "Having detected IL-6 dependent differences in learning and memory, we aimed to uncover the potential mechanism driving this effect in lupus mice." (PMID 38600510, 2024). "Both the lupus-like context in vivo and the co-culture system in vitro induced IL-4 and IL-6 production by basophils." (PMID 38649353, 2024). "Specifically, keratinocytes increase the production of proinflammatory cytokines such as IL-6 in response to IFNκ in lupus and conversely neutralization of IFNκ suppresses their IL-6 production." (PMID 39372419, 2024). "In particular, the cardiac expression of IFI202b and IL6 is also correlated with CV changes, although to a lesser extent, suggesting that these changes may be caused by renal damage and are also influenced by lupus-specific cardiac expression of pro-inflammatory factors." (PMID 37554366, 2023). "We also evaluated the level of serum IL-6, which can be produced by B and T cells, and is elevated in lupus." (PMID 37483626, 2023). "IgG anti-DNA and chromatin antibodies in mice presenting with lupus symptoms are strictly IL-6 dependent, indicating the roles of IL-6 in antibody production." (PMID 37343193, 2023).